IL10 (interleukin 10)
Diseases named in the same sentence as IL10 in open-access papers (continued):
Sharing a sentence is not in itself a finding about the gene and the disease.
tumor (continued). "Additionally, cytokines such as IL-6, IL-10, and TGF-β (transforming growth factor-β) modulate the activity of the immune system in a way that promotes tumor growth." (PMID 40362280, 2025). "Previous studies have confirmed that M2 macrophages inhibit antitumor immune responses through the secretion of immunosuppressive cytokines such as IL-10 and TGF-β, while Tregs support tumor immune evasion by suppressing dendritic cell maturation and effector T cell activity." (PMID 40568593, 2025). "However, B cells, especially regulatory B cells, can produce IL-10, TGF-β, and pro-angiogenic mediators, promoting an immunosuppressive phenotype in neutrophils, macrophages, and CTLs and supporting tumor growth." (PMID 40297580, 2025). "Both TAMs and M-MDSCs secrete cytokines such as IL-6, IL-10, TGF-β, and vascular endothelial growth factor (VEGF), which promote angiogenesis and immune suppression, thereby contributing to the establishment of a pro-inflammatory tumor microenvironment." (PMID 41440517, 2025). "The expression profiles of IL1β, IL10, IL18, TNF-α, TLR4, GATA3, and CD68 in HHV-infected PCa FFPE biopsies indicated an inflammatory environment conducive to immune alteration and potential tumour progression." (PMID 40430084, 2025). "IL24 is a member of the IL10 cytokine family and has been shown to selectively induce apoptosis in tumor cells without affecting normal cells, and it is known for its bystander effects, inducing apoptosis in neighboring tumor cells as well." (PMID 40076725, 2025). "Additionally, neutrophils secrete cytokines including TGF-β, VEGF, OSM, IL-10, and HGF, which directly promote tumor angiogenesis and tumor progression." (PMID 40761249, 2025). "Patients with a poorer PS showed positive interactions among nodes that favored tumor growth, as they were closely correlated with the generation of a proinflammatory environment (IL6), a suppressive microenvironment (IL10), and resistance to immune checkpoints (PD-L2)." (PMID 40149259, 2025). "Some intratumoral microbes may impede DC differentiation and maturation by secreting inhibitory factors, such as IL-10 and TGF-β, or by promoting VEGF secretion by tumor cells." (PMID 41450920, 2025). "However, under the influence of cytokines such as IL-4, IL-10, IL-13, transforming growth factor-beta (TGF-β), and macrophage colony-stimulating factor (M-CSF), TAMs polarize into M2 macrophages, which promote tumor development." (PMID 40131539, 2025). "Cells that were co-cultured with tumor-derived exosomes showed an increase in the expression of levels of cytotoxins and immunosuppressive cytokines, including CTLA-4, TGF-β1, FasL, perforin, granzyme B, and IL-10." (PMID 39857258, 2025). "MDSCs produce factors, such as reactive oxygen species (ROS), nitric oxide (NO), and IL-10, which suppress antigen-specific and nonspecific T-cell responses and promote tumor invasion and angiogenesis." (PMID 40001572, 2025). "TAMs, fibroblasts within the tumor stroma, Trges, and MDSCs are present in TME, and molecules contributing to immunosuppression and the increased expression and activation of TGF-β, IL-10, IL-6, IL-8, prostaglandin E2, VEGF, PD-1, and PD-L1 are secreted by these cells." (PMID 40563393, 2025). "Furthermore, several other marker genes that are known to support tumor growth and creating an immune suppressive environment like IL6, IL10, C1QA, interleukin‐1 receptor antagonist (IL1RN), and KYNU were highly expressed in our Tri culture condition." (PMID 40056038, 2025). "Previous research has shown that CAFs promote tumor progression, potentially by modulating the extracellular matrix and secreting immunosuppressive cytokines or growth factors (such as IL‐10 and TGF‐β), which support tumor proliferation, invasion, and metastasis." (PMID 40900811, 2025).
tumor (continued). "Within the tumor, tumor-specific T cells face persistent antigen stimulation and suppressive factors (tumor growth factor [TGF]-β, IL-10, vascular endothelial growth factor [VEGF], hypoxia, nutrient deprivation), leading to progressive dysfunction, termed T cell exhaustion." (PMID 40327275, 2025). "Moreover, key cytokines and chemokines, including IL-6, IL-10, IL-8, TNF-α, TGF-β, and CCL2/5, demonstrate subtype-specific and context-dependent effects, acting as both tumor-promoting and tumor-suppressing agents through complex signaling networks." (PMID 40909271, 2025). "In advanced stages, however, the balance shifts toward immunosuppressive populations such as M2 macrophages, Th2/Th17 cells, Tregs, and Bregs, which suppress immune responses through the secretion of factors like IL-4, IL-10, IL-17, and TGF-β, thereby facilitating tumor immune escape." (PMID 41384115, 2025). "Additionally, IgG4-polarized macrophages acquire an M2b-like phenotype with high CCL1 and IL-10 production, which facilitates recruitment of CCR8+ Tregs and sustains an immunosuppressive tumor milieu." (PMID 40508133, 2025). "However, tumor cells can suppress DC function by secreting immunosuppressive factors such as TGF-β and IL-10, which alter cytokine secretion patterns." (PMID 40255905, 2025). "Additionally, IL-10’s inhibition of the Th1 response and TGF-β’s inhibition of T-cell activation complement each other, creating a dual mechanism for blocking the anti-tumor immune response." (PMID 40486614, 2025). "However, given that IL-10 has preferential affinity for myeloid cells due to its increased expression of IL-10R, it is likely that NK cell-derived IL-10 could also drive immunosuppression to shut off an immune response to pathogens or within the tumor microenvironment." (PMID 40410571, 2025). "Further, IL-10, a suppressive cytokine that dampens CD4+ T-cell expansion and function, was significantly lower in DCV2-treated groups, suggesting that DCV2 more effectively counters immunosuppression within the tumor microenvironment." (PMID 40573908, 2025). "mRNA expression of CXCL9, iNOS, and IL-12β, anti-tumor macrophage markers, was elevated, while mRNA expression of IFNγ, TNFα, ARG-1, TGFβ, IL-10, and VEGFa, pro-tumor macrophage markers, was significantly lower in TAMs isolated from the prostates of RON∆Epi/TRAMP+ compared to RONF/F/TRAMP+ mice." (PMID 40282397, 2025). "However, studies suggest that reduced IL-10 expression permits increased angiogenesis and heightened activity of VEGF, IL-1β, TNF-α, IL-6, and NF-κB, ultimately enhancing tumor growth." (PMID 40100373, 2025). "Additionally, IL-10 promotes the intratumoral expression of key effector molecules, including IFN-γ, granzymes, and FasL, which are critical for tumor cell elimination." (PMID 40149345, 2025). "Moreover, the study excluded the involvement of immune escape mechanisms related to IL-10, TGF-β, or alterations in PD-L1/MHC I expression on tumor cells." (PMID 41278473, 2025). "Because NOS2 and COX2 promote cytokine release and activation of IL-10 and TGF-β, NOS2 and COX2 tumor expression could complement one another regionally to maintain immune suppression." (PMID 40663402, 2025). "Consequently, TAMs in the HRG tend to polarize toward the M2 phenotype, which suppresses T-cell activity by secreting immunosuppressive factors like IL-10 as well as TGF-β, thereby promoting tumor cell proliferation and metastasis." (PMID 40421217, 2025). "This chronic inflammatory state promotes the release of cytokines (e.g., IL-1β, IL-6, IL-10, IL-18, TNF-α) and growth factors that facilitate tumor cell proliferation, invasion, and angiogenesis, while simultaneously impairing effective immune surveillance against malignant cells." (PMID 41114747, 2025).
tumor (continued). "In the process of acquiring the M2 phenotype, GAMs secrete immunomodulatory and tumor-promoting factors such as TGF-β, epidermal growth factor (EGF), IL-10, and the proteolytic enzymes MMP-2 and MMP-9, thereby reinforcing an immunosuppressive tumor milieu within the glioblastoma microenvironment." (PMID 41479886, 2025). "However, Treg cells inhibit immune responses by secreting IL-10 and TGF-β and can directly interact with effector T cells to suppress the activity of antitumor immune cells, aiding tumor cells in evading immune surveillance and attack." (PMID 41181157, 2025). "Furthermore, TFPI2 may promote M2-type tumor-associated macrophages (TAMs) via PPARγ, which support tumor growth through immune evasion, angiogenesis, and ECM remodeling by releasing factors like epidermal growth factor (EGF), hepatocyte growth factor (HGF), VEGF, MMPs, IL-10, and TGF-β." (PMID 40361374, 2025). "However, the interaction between tumor cells and immune cells within the inflammatory microenvironment, along with various immune checkpoints such as IDO, IL-10, TGF-β, PD-1, and CTLA-4, results in T cell dysfunction." (PMID 40688079, 2025). "M2-TAMs secrete IL-10, TGF-β, and PGE2, and promote tumor angiogenesis and tissue remodeling." (PMID 40109347, 2025). "On the other hand, Tregs are FOXP3- and CD25-positive CD4+ T lymphocytes (CD4+CD25+FoxP3+) that promote immunosuppression and a tolerogenic tumor microenvironment by secreting inhibitory cytokines such as TGF-β and IL-10 and by interacting with other immune cells." (PMID 40805183, 2025). "IL-10 is generally considered as an immunosuppressive cytokine in the TME, so the decreased level of IL-10 is unlikely to be the reason for the accelerated tumor outgrowth, while the role of IL-4 in antitumor immunity is ambiguous." (PMID 40759573, 2025). "Immunosuppressive factors such as TGF-β, IDO, IL-10, VEGF, and PGE2 in the TME impair the maturation and functionality of DCs, enabling immune evasion and tumor progression, and neutralizing these factors promotes DC recruitment, survival, activation, and antigen-presenting capacity." (PMID 41430039, 2025). "Additionally, overexpression of IL-10 enhances OXPHOS in CAR-T cells, improves mitochondrial function, and thereby helps control tumor recurrence." (PMID 40155378, 2025). "Additionally, they secrete arginase II (Arg2), chitinase-3-like protein 1 (CHI3L1/YKL-40), and the anti-inflammatory cytokines IL-10 and TGF-β, which contribute to their immunosuppressive and tumor-promoting roles." (PMID 40771826, 2025). "Tumor-secreted cytokines like TGF-β and IL-10 amplify immune checkpoint-mediated suppression." (PMID 41244711, 2025). "Other contributing factors may include immunosuppressive cytokines (e.g., interleukin-10, TGF-β), metabolic stress within the tumor microenvironment, hormonal influences, and insufficient CD4+ T-cell help during early priming." (PMID 40723153, 2025). "In addition, tumour-derived cytokines such as TGF-β, IL-10 and IL-6 have been shown to inhibit DC survival and proliferation." (PMID 38384463, 2024). "IL-10 and IL-21, but not IL-6, activate STAT3, promote tumor-specific Texterm cell-associated gene expression, and suppress TexProg cell-related gene expression, resulting in the development and enhanced effector functions of Texint cells in tumors." (PMID 38582965, 2024). "Additionally, ERK5 inhibition drives macrophages to switch from an M2 to an M1 phenotype, accompanied by reduced IL-10 and increased TNF-α secretion, further amplifying anti-tumor immune responses." (PMID 39575419, 2024). "Given that IL-10 and TGFβ modulate tumor cell biology such as EMT, it is plausible that these CD73 positive NK cells within the tumor microenvironment influence the metastatic potential of tumor cells." (PMID 38191418, 2024).
tumor (continued). "For example, low expression of MHC I and MHC II on the surface of tumor cells or expression of immunosuppressive molecules such as vascular endothelial growth factor (VEGF), interleukin-10 (IL-10), Fas ligand (Fas-L), TGF-β and prostaglandin E2 (PGE2) to mediate immune escape." (PMID 38633106, 2024). "Moreover, NK cells were also involved in the reshaping of the tumor microenvironment into one responsive to ICB through sensitization therapy consisting of IFNγ, anti-IL-10 and TLR3 agonist poly-IC in subcutaneous tumor models." (PMID 39551601, 2024). "Finally, M2d macrophages release IL-10 and VEGF and thus promote tumor progression and angiogenesis." (PMID 38397187, 2024). "M2 macrophages express high levels of IL-10, TGF-β, ARG1, and other related factors that promote tumor growth, which can not only induce immune escape, angiogenesis, tumor growth, and metastasis but also lead to resistance to checkpoint inhibitors or adoptive T cell immunotherapy." (PMID 39596288, 2024). "Moreover, blockade of systemic C3aR strongly suppressed the increase in the secretion of TGF‐β, IL10, and IL8, and the elevated level of C3a induced by CDK9i, indicating there existed a tumor‐host interaction." (PMID 39254172, 2024). "Tumor-infiltrating CD4+CD25+Treg cells were found to directly suppress the cytotoxic ability and IFN-γ secretion of γδ T cells in vitro, dependent on TGF-b and IL-10." (PMID 38338658, 2024). "In addition, in response to factors secreted in the TME, Tregs are recruited from the circulation, further contributing to diminishing tumor immune surveillance by secreting IL-10 and TGF-β, or possibly by killing anti-tumor effectors and APCs." (PMID 39682686, 2024). "IL-10, an anti-inflammatory cytokine, creates an immunosuppressive environment in non-small cell lung cancer (NSCLC), inducing resistance to apoptosis, angiogenesis, tumor growth and metastasis." (PMID 38521953, 2024). "Furthermore, some natural products can inhibit immunosuppressive factor secretion: IL-10, TGF-β; promote anti-tumor factor secretion: IL-2, IL-5, IL-6, IL-12; reduce immunosuppressive immune cells: Treg, M2 microphage; increase anti-tumor CD8+ T-cells." (PMID 38426097, 2024). "TAMs participate in tumor growth and metastasis by releasing TNF-α, TGF‐β, IL6, IL10, and VEGF-A." (PMID 39845973, 2024). "Moreover, MDSCs produced angiogenic and immunosuppressive chemicals that contribute to TIME, secreting IL-10, arginase, and COX2 aiming to restrain anti-tumor cell activity significantly." (PMID 38649887, 2024). "T helper (Th) cells play a crucial role in enhancing anti-tumor and anti-inflammatory immune responses by releasing various cytokines such as TNF-α, Granulocyte-Macrophage Colony-Stimulating Factor (GM-CSF), IL-2, IL-6, IL-10, IL-21, and others." (PMID 38755133, 2024). "Several factors in the PDAC microenvironment contribute to impaired DC function: tumor-derived TGF-β, IL-10, and IL-6 suppress DC survival and proliferation, MDSCs inhibit DC maturation, and a subset of immunosuppressive CD11b+ DCs can induce Treg generation and cytotoxic T cell (CTL) suppression." (PMID 39178856, 2024). "SCC tissue and proximal healthy tissue also showed different responses to direct CP ex vivo, with higher levels of cytochrome c, higher IL10, TNFα, and IFNγ release, and lower IL22 released from tumour tissue indicating significantly increased stress and apoptosis in malignant tissues." (PMID 38785562, 2024). "Repression of tumor immunity, within the TME, can also occur via tumor cell secretion of paracrine-acting factors (e.g., IL-10 and PGE2), resulting in polarization of monocytic MDSCs into M2-like TAMs; analogously, inhibition of prostaglandin synthesis (via COX2 inhibition) reversed this effect." (PMID 39410029, 2024).
tumor (continued). "These include the downregulation of tumor antigens to reduce detection by T-cells, the secretion of immunosuppressive molecules such as TGF-β and IL-10 that create a hostile environment for immune cells, and the manipulation of immune checkpoints to inhibit T-cell activation." (PMID 39161779, 2024). "Interestingly, it was observed that, in addition to being secreted by tumor cells, these same MDSC-activating factors with the addition of IL1β and IL10 were also secreted by T-MDSCs to self-promote their own proliferation and infiltration." (PMID 39763643, 2024). "During the tumor formation in B16F10 cell-challenged C57BL/6 mice, serum levels of several cytokines were monitored using ELISA to evaluate the effect of Hcs treatment: IL4, IL10, and IFNγ." (PMID 38786612, 2024). "IL-10 and transforming growth factor beta (TGF-β) are two anti-inflammatory cytokines that appear to play a role in impairing the activity of cytotoxic T cells in the tumor microenvironment." (PMID 39273323, 2024). "Immunosuppressive cytokines (IL-10, IL-35, and TGF-β) produced by Tregs have the capacity to both drive CD8+ T cells to cease becoming Teffs and deliver immunological escape indications to tumor cells." (PMID 39372416, 2024). "Moreover, we discovered alterations in the expression of immune-regulatory genes in cells devoid of C22orf46 expression, enhancing tumor visibility to the immune system such as CXCL11, ICAM-1, or IL-10." (PMID 38228372, 2024). "Additionally, immunosuppressive cells such as regulatory B cells, Tregs, and MDSCs in the TME inhibit effector T cells and NK cells by secreting immunosuppressive factors like IL-10 and TGF-β, promoting tumor growth and metastasis." (PMID 39741315, 2024). "Concomitant anti-IL-10 treatment enhanced efficacy of cyclophosphamide and bone marrow-derived dendritic cell transfer therapy via limiting MDSC suppressive functions allowing enhanced NK cell anti-tumour effector function." (PMID 38464388, 2024). "Additionally, TAMs secrete immunosuppressive factors such as IL-10 and TGF-β, which inhibit the activity of effector T cells and natural killer (NK) cells, thereby promoting tumor immune evasion." (PMID 39290697, 2024). "Our results indicate that, compared with tumor controls, TAMs infiltrating Egfl6+ tumors exhibited upregulation of Cxcl2, whereas PMN-MDSCs isolated from Egfl6+ tumors showed upregulation of both IL-10 and Cxcl2." (PMID 39312740, 2024). "During tumor progression, the proliferation and invasion of tumor cells as well as the EMT process are controlled by TME-mediated secretion of several growth factors and cytokines including TGF-β, IL-6, IL-8, IL-10 and VEGF." (PMID 39335188, 2024). "Shift to the complexity of the tumor microenvironment: Research has begun to emphasize the role of macrophages as key components of the tumor microenvironment, particularly focusing on blocking the STAT3/IL-10 pathway related to IL-10, which has seen extensive study in recent years." (PMID 39034998, 2024). "TANs have pro-tumor activity by producing ARG1, IL-10, TGF-β, and VEGF, and inhibiting cytotoxic T cells by expressing higher levels of immunosuppressive molecules, such as PD-L1, ARG1, and IDO, and lower of anti-tumor molecules, such as ROS and TNF-α." (PMID 39430759, 2024). "IL‐10 and transforming growth factor‐β (TGF‐β) were found downregulated in OART group, consistent with decreased M2 phenotype TAMs, indicating an immune reverse in tumor microenvironment." (PMID 38774917, 2024). "In the OC tumor microenvironment (TME), IL-10 was found to be secreted by mostly innate immune cells, such as monocytes, dendritic cells, macrophages and natural killer cells, and also adaptive immune cells such as CD4+ and CD8+ T cells, Th17 cells and B cells." (PMID 39199610, 2024). "Tumor cells’ secretion of macrophage colony-stimulating factor (M-CSF) induces fatty acid synthase (FASN) in TAMs, which, in turn, promotes the production and secretion of immunosuppressive IL-10." (PMID 39119332, 2024).